IGSF9 (immunoglobulin superfamily member 9)
Description:
Functions in dendrite outgrowth and synapse maturation.
Synonyms: IgSF9A; KIAA1355; NRT1; FP18798
Tractability: Antibody: UniProt places it where antibodies can reach, with medium confidence; UniProt predicts a signal peptide or a membrane-spanning region; its Gene Ontology location is reachable by antibodies, with medium confidence.
Gene: Protein-coding gene on chromosome 1 (159,927,039 to 159,949,468, reverse strand). Ensembl gene ENSG00000085552.
Subcellular location: Cell membrane; Synapse
Gene Ontology:
Molecular function: cell-cell adhesion mediator activity
Biological process: axon guidance; dendrite self-avoidance; homophilic cell-cell adhesion; regulation of synapse maturation; regulation of synapse organization
Cellular component: axon; plasma membrane; dendrite; glutamatergic synapse; inhibitory synapse; postsynaptic density membrane; synapse
Genetic constraint (gnomAD): Loss-of-function variants: 87 observed, 113.18 expected, observed/expected ratio (o/e) 0.77, 90% interval 0.64 to 0.92. The upper end of that interval is the gene's LOEUF score, 0.92, which puts it in group 3 of 6, group 1 being the genes least tolerant of losing a copy. Missense variants: 1,456 observed, 1,490.3 expected, observed/expected ratio (o/e) 0.98, 90% interval 0.94 to 1.02. Synonymous variants: 640 observed, 622.98 expected, observed/expected ratio (o/e) 1.03, 90% interval 0.96 to 1.1.
Homologues: Orthologues: chimpanzee IGSF9 (99% identical), macaque IGSF9 (98% identical), dog IGSF9 (90% identical), pig IGSF9 (90% identical), guinea pig IGSF9 (90% identical), mouse Igsf9 (88% identical), rat Igsf9 (87% identical), rabbit IGSF9 (79% identical), tropical clawed frog igsf9 (51% identical). Paralogues in human: IGSF9B (41% identical), SDK2 (17% identical), SDK1 (17% identical), ROBO2 (17% identical), ROBO1 (17% identical), ROBO3 (16% identical), HMCN2 (16% identical), NEO1 (16% identical), DCC (16% identical), IGSF10 (15% identical), IGDCC4 (15% identical), MXRA5 (15% identical), and 24 more.
Diseases named in the same sentence as IGSF9 in open-access papers:
IGSF9 is named in the same sentence as 29 diseases in open-access papers, as found by Europe PMC text mining. Sharing a sentence is not in itself a finding about the gene and the disease. The quoted sentences say what the papers report.
breast carcinoma (3 papers, 2022 to 2024). "In GSE16446 database, we found that low IGSF9 expression in breast cancer patients was associated with worse relapse free survival (RFS) (P = 0.037) and overall survival (OS) (P = 0.019), compared with those of high IGSF9 expression." (PMID 36088502, 2022). "Together, these data indicate that IGSF9 loss induces metastasis of breast cancer via activating FAK/AKT signaling." (PMID 36088502, 2022). "Loss of IGSF9 promotes breast cancer metastasis in vitro and in vivo." (PMID 36088502, 2022). "Loss of IGSF9 is associated with frequent metastasis and poor prognosis of breast cancer patients." (PMID 36088502, 2022). "However, the molecular mechanisms underlying IGSF9 expression and cancers remain elusive, especially in breast cancer." (PMID 36088502, 2022). "Together, these data indicated that loss of IGSF9 promoted breast cancer metastasis in vitro." (PMID 36088502, 2022). "Loss of IGSF9 correlates with breast cancer metastasis and poor prognosis." (PMID 36088502, 2022). "In patients with breast cancer, it was shown that IGSF9 interacts with FAK, which led to inhibition of downstream effects of the FAK/AKT signalling pathway including epithelial mesenchymal transition." (PMID 39426127, 2024). "The typical EMT phenotypes, down-regulation of E-cadherin and ZO-1, and up-regulation of N-cadherin and MMP2, were found as well in IGSF9-knowdown breast cancer cells with western blot analysis and immunofluorescence assay." (PMID 36088502, 2022). "IGSF9 expression was markedly decreased in 75% (21/28) of breast cancer tumors, comparing with the corresponding adjacent normal tissues." (PMID 36088502, 2022). "Consistently, transwell invasion assays indicated that over-expression of IGSF9 led to a significant decrease of cell invasion ability, while IGSF9 knockdown resulted in an increase of cell invasion in breast cancer cells." (PMID 36088502, 2022). "IGSF9 mRNA expression in 28 pairs of breast cancer tumors and adjacent normal tissues were detected by qRT-PCR." (PMID 36088502, 2022). "PND1186, FAK inhibitor, inhibits breast cancer metastasis induced by IGSF9 knockdown in vitro and in vivo." (PMID 36088502, 2022). "CHX chase experiments showed that IGSF9 protein became less stable in the breast cancer cell than that in normal mammary cell MCF-10A." (PMID 36088502, 2022). "IGSF9 shows low expression in liver hepatocellular carcinoma, skin cutaneous melanoma, testicular germ cell tumors, as well as in breast cancer which was reported in the present study." (PMID 36088502, 2022). "This study discovered a feasible prognostic biomarker IGSF9, and at the same time sheds light on the potential new strategies for developing treatment for breast cancer patients." (PMID 36088502, 2022). "Consistently, western blot analysis also showed a significant down-regulation of IGSF9 in breast cancer tumors (P < 0.001)." (PMID 36088502, 2022). "To explore genomic alteration of IGSF9 in breast cancer, we analyzed the sequences in 9555 breast cancer cases from cBioportal database (2012 to 2021)." (PMID 36088502, 2022).
breast carcinoma (continued). "In contrary, EMT phenotypes were inhibited in IGSF9-overexpressed breast cancer cells." (PMID 36088502, 2022). "We found that PND1186, a FAK inhibitor, could inhibit breast cancer metastasis induced by IGSF9 knockdown in vitro and in vivo." (PMID 36088502, 2022). "We next tested the stability of IGSF9 protein in breast cancer." (PMID 36088502, 2022). "Loss of IGSF9 enhances FAK kinase activity, activates AKT, leading to breast cancer metastasis." (PMID 36088502, 2022). "mRNA expression of IGSF9 mutations was uniformly distributed in three indicated datasets, indicating that IGSF9 mutations did not affect its mRNA level in breast cancer." (PMID 36088502, 2022). "FAK inhibitor PND1186 could inhibit IGSF9 knockdown-induced breast cancer metastasis in vitro and in vivo." (PMID 36088502, 2022). "Taken together, these data indicated that decreased IGSF9 expression correlated with poor prognosis and metastasis and could be a valuable indicator for poor prognosis in breast cancer patients." (PMID 36088502, 2022). "IGSF9 inhibits breast cancer metastasis through FAK signaling." (PMID 36088502, 2022). "IGSF9 could serve as a prognostic marker and potential therapeutic target for breast cancer." (PMID 36088502, 2022). "IGSF9/FAK axis might serve as a potential target for breast cancer treatment." (PMID 36088502, 2022). "To investigate the role of IGSF9 in proliferation and metastasis of breast cancer cells, we stably over-expressed IGSF9 in MCF-7 and T47D cell lines, and knocked down IGSF9 in MDA-MB-231 and MDA-MB-468 cell lines." (PMID 36088502, 2022). "However, neither hsa-miR-8485 nor hsa-miR-2355-5p inhibited luciferase activity of IGSF9 3′-UTR, suggesting that these two miRNAs were not involved in IGSF9 regulation in breast cancer." (PMID 36088502, 2022).
lymph node metastasis (3 papers, 2022 to 2024). "The IHC results also showed that the expression of the IGSF9, PRDM16, and ALDH2 proteins was significantly associated with a higher level of lymph node metastasis." (PMID 35013309, 2022). "Notably, low IGSF9 expression was significantly correlated with lymph node metastasis (P = 0.023) and advanced TNM (tumor-node-metastasis) staging (P = 0.030), but not age, tumor size or tumor differentiation." (PMID 36088502, 2022). "Reduced copy numbers of IGSF9 and PRDM16 and the increased copy number of ALDH2 were intricately intertwined with lymph node metastasis and reduced survival rates in IMPC patients." (PMID 38181281, 2024). "The correlation analyses showed that IGSF9 and PRDM16 protein levels inversely correlated with lymph node metastasis (IGSF9, R = −0.32, P < 0.01; PRDM16, R = −0.336, P < 0.01), while ALDH2 protein expression positively correlated with lymph node metastasis (ALDH2, R = 0.262, P < 0.05)." (PMID 35013309, 2022).
endometrial cancer (2 papers, 2018 to 2020). Primary or metastatic malignant neoplasm involving the endometrium (mucous membrane that lines the endometrial cavity). "To date, there is one published report on over-expression of IGSF9 associated with poor PFS in endometrial cancer tissue." (PMID 33061850, 2020). "Focusing on IGSF9, an adhesion molecule that has not been characterized in connection with cancer pathology, we confirmed the overexpression of IGSF9 in endometrial cancer and found an association with myometrial invasion and poor outcome." (PMID 29666643, 2018). "Reanalysis of RNA-seq dataset from The Cancer Genome Atlas shows higher expression of IGSF9 in endometrial cancer versus normal control and expression was associated with poor prognosis." (PMID 29666643, 2018). "Overexpression of IGSF9 is an indicator of poor prognosis in endometrial cancer." (PMID 29666643, 2018). "Moreover, IGSF9 overexpression is also associated with poor prognosis in several other cancer types, including brain lower grade glioma, skin cutaneous melanoma, and thymoma, suggesting that the significance of IGSF9 in cancer pathology is likely not limited to endometrial cancer." (PMID 29666643, 2018).
skin cutaneous melanoma (2 papers, 2018 to 2022). "A statistically significant association of IGSF9 overexpression and poor overall survival was also observed in thymoma, skin cutaneous melanoma, and brain lower grade glioma." (PMID 29666643, 2018).
bladder urothelial carcinoma (1 paper, 2022). "On the other hand, IGSF9 shows high expression in bladder urothelial carcinoma, ovarian serous cystadenocarcinoma, pancreatic adenocarcinoma, uterine corpus endometrial carcinoma." (PMID 36088502, 2022).
colon adenocarcinoma (1 paper, 2018). "In contrast, IGSF9 expression is lower in cancer versus normal control in rectum adenocarcinoma and colon adenocarcinoma." (PMID 29666643, 2018).
colorectal cancer (1 paper, 2018). A primary or metastatic malignant neoplasm that affects the colon or rectum. "Interestingly we observed the opposite relationship in colorectal cancer, wherein IGSF9 was expressed at lower levels in cancer versus normal, suggesting a topic to be further studied." (PMID 29666643, 2018).
endometrioid carcinoma (1 paper, 2018). "The expression pattern as revealed by our immunohistochemical analyses in endometrioid carcinoma confirms the localization of IGSF9 on the cellular membrane and in the cytoplasm." (PMID 29666643, 2018). "The gene IGSF9 was chosen for further characterization with immunohistochemical staining of a larger cohort of human endometrioid carcinoma tissues." (PMID 29666643, 2018).
endometrioid endometrial carcinoma (1 paper, 2018). "Focusing on the overexpressed gene IGSF9, we explored its associations with clinicopathologic characteristics in endometrioid endometrial carcinoma." (PMID 29666643, 2018). "As IGSF9 is the only common gene from both analyses, we focused on IGSF9 and explored the association of IGSF9 protein expression with clinicopathological characteristics in endometrioid endometrial carcinoma." (PMID 29666643, 2018).
fibrosis (1 paper, 2024). the formation of excess fibrous connective tissue in an organ or tissue in a reparative or reactive process. "For example, ADGRG1 and IGSF9, both upregulated in PLHIV with fibrosis, were positively correlated with T2DM, presence of carotid plaques, prior myocardial infarction, duration of HIV and ART, and prior exposure to D-drugs and INSTI." (PMID 39426127, 2024).
liver fibrosis (1 paper, 2024). "In addition, we identified a protein, IGSF9, strongly related to liver fibrosis and steatosis across BMI categories." (PMID 39426127, 2024).
myocardial infarction (1 paper, 2024). Gross necrosis of the myocardium, as a result of interruption of the blood supply to the area, as in coronary thrombosis. "IGSF9 concentrations gradually increased by steatosis grade and correlated with prior myocardial infarction, presence of carotid plaques, T2DM, HIV-specific characteristics and prior and current ART." (PMID 39426127, 2024).
steatosis (1 paper, 2024). Increased lipid within the cytoplasm of cells. "Immunoglobulin superfamily member 9 (IGSF9) was amongst the top DEP associated with both steatosis and fibrosis." (PMID 39426127, 2024). "We identified the protein IGSF9 as a key protein associated with steatosis and fibrosis in PLHIV." (PMID 39426127, 2024). "Stratifying by BMI revealed 8/2367 DEP associated with steatosis in lean- and 12/2367 DEP in overweight/obese individuals, with two shared DEP (IGSF9 and GHR)." (PMID 39426127, 2024). "Moreover, IGSF9 has a central position in the protein–protein network of DEP in PLHIV with steatosis." (PMID 39426127, 2024). "Of note, IGSF9, ADAMTSL2, KRT18, and RIDA were associated with both steatosis and fibrosis." (PMID 39426127, 2024). "IGSF9 was amongst the top DEP for fibrosis and steatosis across BMI categories." (PMID 39426127, 2024). "In a protein–protein interaction network, IGSF9 was found to have a central position, being correlated to FGF21, CES1, MAMDC4, and afamin (AFM) in PLHIV with steatosis, and to AFM and GHR in those without steatosis." (PMID 39426127, 2024).
tumor (6 papers, 2018 to 2025). "To explore the molecular mechanisms underlying the tumor suppressive effect of IGSF9, we analyzed the differential gene expression between IGSF9 high and low expression samples in GSE27830." (PMID 36088502, 2022). "Interestingly, the reduced level of genus Enterococcus in tumour tissues was also found to be associated with the down-regulated expression of IGSF9 (Immunoglobulin Superfamily Member 9), which contributes to regulating immune cell activation." (PMID 32321427, 2020). "Targeting IGSF9 can restore T‐cell function and inhibit tumor growth, suggesting that IGSF9 is a novel immune checkpoint target." (PMID 41346571, 2025). "Transwell migration and invasion assays also demonstrated that administration of PND1186 dramatically reversed IGSF9 knockdown-induced tumor migration and invasion of MDA-MB-231 and MDA-MB-468 cells." (PMID 36088502, 2022). "The numbers of metastatic lesions in lungs showed that IGSF9 knockdown accelerated tumor metastasis, which could be reversed by PND1186 treatment." (PMID 36088502, 2022). "Calmodulin is involved in tumor metastasis, and our GSEA result also shows that IGSF9 may cause metastasis of NPC cells through Akt signaling pathway." (PMID 33061850, 2020). "In Yap1KD; Gp130FF tumor organoids, we found reduced transcript levels for Igsf9 (marker for cell proliferation), Cyp2c65, (lipid and glucose metabolism), Ptgr1 and Sult1c2 (metabolite biosynthesis), and Clca1 (mucosal defence) when compared with Yap1WT; Gp130FF tumor." (PMID 37957015, 2024).
cancer (4 papers, 2018 to 2025). A tumor composed of atypical neoplastic, often pleomorphic cells that invade other tissues. "IGSF9 and IGFBP2 are implicated in multiple cancers and are considered potential diagnostic or prognostic markers and treatment targets." (PMID 41071435, 2025). "Previous studies reported that IGSF9 was aberrantly expressed in different cancer types, such as down-regulation in melanoma, colorectal familial adenomatous polyposis, and upregulation in gallbladder cancer, ovarian cancer, and endometrial cancer." (PMID 36088502, 2022). "Paired comparison of relative IGSF9 expression shows significantly enhanced staining in cancer tissues relative to controls with values of 0.448 versus 0.200, respectively (p value = 0.008 by the Wilcoxon test)." (PMID 29666643, 2018). "As further characterization of IGSF9 expression in relation to cancer microscopic features requires immunohistochemistry, we evaluated IGSF9 expression at protein level in FFPE materials from 56 patients." (PMID 29666643, 2018). "The expression level of IGSF9 in cancer cells was significantly higher than that in control glandular cells in paired tissue samples from the same patients (p = 0.008) or in overall comparison between cancer and the control (p = 0.003)." (PMID 29666643, 2018). "The role of IGSF9 in cancer appears to be tissue context-specific." (PMID 36088502, 2022). "This event would further decrease IGSF9 expression and facilitate cancer metastasis." (PMID 36088502, 2022). "Nevertheless, the reduced abundance of genus Paeniclostridium and genus Enterococcus in cancer tissues also exhibited significant associations with the expression difference of PLCB1 (r = 0.995, p-value = 0.01, df = 2) and IGSF9, respectively (r = − 0.997, p-value = 0.003, df = 2)." (PMID 32321427, 2020). "Further studies on the role of IGSF9 in cancer pathology are warranted." (PMID 29666643, 2018). "The expression of IGSF9 is higher in cancer than that in normal or benign endometrial tissue." (PMID 29666643, 2018). "A decrease of IGSF9 releases FAK, activates FAK/AKT signaling and promotes EMT process, resulting in cancer metastasis." (PMID 36088502, 2022). "We confirmed the differential expression of IGSF9 in cancer versus noncancer tissues with materials from a cohort of 56 patients." (PMID 29666643, 2018). "The positivity of IGSF9 is also higher in cancer with myometrium invasion than those without, likely an indicator of cancer aggressiveness." (PMID 29666643, 2018). "We first performed quantitative PCR to confirm the differential expression of IGSF9 in cancer versus noncancer endometrial tissues." (PMID 29666643, 2018). "To date, there are no published reports on IGSF9 in any type of cancer tissue." (PMID 29666643, 2018).
IGSF9 also shares sentences with these, for which no sentence is quoted: infection (2 papers); acute myeloid leukemia (1); breast invasive carcinoma (1); Epstein-Barr virus infection (1); nasopharyngeal carcinoma (1); Niemann-Pick disease type C (1); ovarian serous cystadenocarcinoma (1); pancreatic adenocarcinoma (1); rectum adenocarcinoma (1); testicular germ cell tumor (1); thymoma (1); type 2 diabetes mellitus (1); uterine corpus endometrial carcinoma (1); viral infection (1).